DNAJC25 (DnaJ heat shock protein family (Hsp40) member C25)
Synonyms: bA16L21.2.1
Tractability: Antibody: UniProt predicts a signal peptide or a membrane-spanning region. PROTAC: its protein half-life has been measured.
Gene: Protein-coding gene on chromosome 9 (111,631,334 to 111,654,351, forward strand). Ensembl gene ENSG00000059769.
Subcellular location: Membrane
Subcellular location (Human Protein Atlas): Nucleoplasm; Cytosol
Gene Ontology:
Biological process: protein folding
Cellular component: endoplasmic reticulum membrane; membrane
Genetic constraint (gnomAD): Loss-of-function variants: 24 observed, 35.11 expected, observed/expected ratio (o/e) 0.68, 90% interval 0.49 to 0.96. The synonymous counts are far from expectation, so gnomAD's model fits this gene poorly and the ratio says little. Missense variants: 364 observed, 377.08 expected, observed/expected ratio (o/e) 0.97, 90% interval 0.88 to 1.05. Synonymous variants: 167 observed, 132.35 expected, observed/expected ratio (o/e) 1.26, 90% interval 1.11 to 1.43.
Homologues: Orthologues: chimpanzee DNAJC25 (99% identical), macaque DNAJC25 (97% identical), dog DNAJC25 (93% identical), rabbit DNAJC25 (92% identical), guinea pig DNAJC25 (92% identical), pig DNAJC25 (91% identical), mouse Dnajc25 (91% identical), rat Dnajc25 (91% identical), tropical clawed frog dnajc25 (72% identical), zebrafish dnajc25 (66% identical), Drosophila melanogaster CG7872 (49% identical), Caenorhabditis elegans dnj-2 (36% identical), and 3 more. Paralogues in human: DNAJC13 (21% identical), DNAJC1 (18% identical), DNAJC16 (17% identical), DNAJC11 (16% identical), DNAJC10 (16% identical), DNAJC7 (16% identical), DNAJC14 (15% identical), DNAJC2 (15% identical), DNAJC21 (14% identical), DNAJC17 (14% identical), DNAJC18 (12% identical), DNAJC3 (12% identical), and 8 more.
Diseases named in the same sentence as DNAJC25 in open-access papers:
DNAJC25 is named in the same sentence as 5 diseases in open-access papers, as found by Europe PMC text mining. Sharing a sentence is not in itself a finding about the gene and the disease. The quoted sentences say what the papers report.
liver cancer (2 papers, 2017 to 2021). An epithelial or non-epithelial malignant neoplasm that arises from the liver. "In liver cancers, DNAJC25 mRNA expression is markedly reduced, while its overexpression induces apoptosis and inhibits colony formation of liver cancer cells." (PMID 34948322, 2021). "In liver cancer, the expression of another potential tumor-suppressor member, DNAJC25 is markedly reduced, whereas overexpression led to significant increase in apoptosis and reduction in number of surviving liver cancer cell colonies." (PMID 28914774, 2017).
breast carcinoma (1 paper, 2021). "In silico analyses suggest that DNAJC25 mRNA expression is also reduced in breast cancer tissues, and high DNAJC25 mRNA expression is correlated with favorable post-progression survival in breast cancer." (PMID 34948322, 2021).
hepatocellular carcinoma (1 paper, 2025). A malignant tumor that arises from hepatocytes. "The latest research shows that RNF149 can accelerate the progression of hepatocellular carcinoma by ubiquitinating the substrate DnaJ homolog subfamily C member 25 (DNAJC25)." (PMID 40245000, 2025).
tumor (2 papers, 2021 to 2023). "Furthermore, DNAJC25 expression was also negatively associated with increased malignancy of HCC, and high expression of DNAJC25 in tumor tissues indicated longer OS and DFS." (PMID 37958377, 2023).
cancer (1 paper, 2020). A tumor composed of atypical neoplastic, often pleomorphic cells that invade other tissues. "About 80% (65/82) of HSPs showed aberrant expression, ranging from one cancer type (e.g., DNAJC25) to 15 cancer types (e.g., HSPB6)." (PMID 33225964, 2020). "In the HSP40 family, DNAJC25 and DNAJC8 were positively associated with stemness in 16 and 14 cancers, respectively, while DNAJC11 and DNAJC3 were negatively associated with stemness in 25 and 25 cancers, respectively." (PMID 33225964, 2020).